CRP (C-reactive protein)
Diseases named in the same sentence as CRP in open-access papers (continued):
Sharing a sentence is not in itself a finding about the gene and the disease.
Hypertension (continued). "The second of three regression equations confirms literature available on shorter LTL in subjects reporting a history of CVD, hypertension included, binge drinking, and in those with higher values of the CRP, the systemic inflammation marker." (PMID 28536575, 2017). "In the simultaneous analysis, the first of three regressions shows that PTX3 negatively associates with BMI, CRP, and history of CVD hypertension included, suggesting that PTX3 is modulated by several aging conditions and/or disorders." (PMID 28536575, 2017). "When the sample was split by the presence of hypertension and hyperglycemia, CRP levels were significantly elevated in both disorders (P < 0.01 and P = 0.04, respectively)." (PMID 28947597, 2017). "After adjustment according to potential confounders such as age, sex, and smoking, hypertension, type 2 DM, dyslipidemia, hcy, and CRP, the odds ratios (and 95 %CIs) for large cerebral artery stenosis were analyzed." (PMID 28978025, 2017). "The aim of this study was to compare the relative utility of apnea/hypopnea index (AHI) versus a biomarker of inflammation, C‐reactive protein (CRP), in identifying the presence and severity of hypertension and hyperglycemia." (PMID 28947597, 2017). "In summary, our preliminary study suggests that CRP is a stronger marker of hypertension and hyperglycemia compared to AHI in middle‐aged adults with mild‐to‐moderate obstructive sleep apnea." (PMID 28947597, 2017). "Higher intraocular pressure was significantly associated with young age (P = .010), male sex (P = .006), current smoking habit (P = .033), central obesity (P = .002), hypertension (P < .001), hypertriglyceridemia (P = .019), and higher CRP (P = .002)." (PMID 28885336, 2017). "Univariable analysis determined that age, hypertension, CRP, total Cholesterol, LDL-Cholesterol, Framingham score and CAC were independently associated with CV events." (PMID 28962654, 2017). "In this model AAR > 1.67, sex, type 2 diabetes, age > 75 years, coexistence of congestive heart failure, arterial hypertension, CRP, and renal impairment were included." (PMID 27310963, 2016). "Compared to patients without RH, patients with RH were more elderly, had more males, smokers, longer duration of hypertension, higher plasma C-reactive protein (CRP) level and Lp-PLA2 activity (P < 0.05 for all comparisons)." (PMID 26801405, 2016). "As a marker of inflammation, CRP is closely related to many CVDs such as hypertension, atherosclerosis, coronary heart disease, and myocardial infarction." (PMID 27403433, 2016). "Three of these genes (Crp, C-reactive protein, pentraxin-related; Fabp1, fatty acid binding protein 1, liver; Ucp1, uncoupling protein 1 (mitochondrial, proton carrier)) are known as related to hypertension development." (PMID 28105924, 2016). "Univariate logistic regression analysis demonstrated that advanced age, female sex, increased BMI, hypertension, dyslipidemia, high CRP values, low eGFR, and KT were significant predictors of HPR in patients on clopidogrel maintenance therapy." (PMID 27278793, 2016). "Recently, it has become evident that the immune system and inflammatory markers such as Interleukin-6, Tumor necrosis factor alpha and C-reactive protein are also essential in the pathogenesis of hypertension." (PMID 26989902, 2016). "Compared to the healthy controls, partly due to exclusion criteria for controls, significantly more ICU patients had a history of cardiovascular disease or hypertension and higher levels of CRP, glucose, and creatinine at inclusion." (PMID 27529340, 2016). "As compared to patients without RH, those with RH have more co-morbidities such as more elderly, larger percentages of male patients and smokers, longer duration of hypertension and have higher plasma CRP level." (PMID 26801405, 2016). "Hypertension with high homocysteine (HHcy) (H-type hypertension) and C reactive protein (CRP) can increase the incidence of ischemic stroke." (PMID 27164124, 2016).
Hypertension (continued). "And the strength of this association remained similar after further adjusted for body mass index (BMI), smoking, hypertension duration, CRP, TC, LDL-C and anti-hypertensive drugs (model 2), with OR of 2.02 (95 % CI 1.85–2.06, P < 0.05)." (PMID 26801405, 2016). "Control of all results through adjustment for the same confounding factors showed marginal correlations of cfPWV with CRP [0.105 95 % CI (−0.410 to 0.003), p = 0.053] and arterial hypertension [0.566 95 % CI (−0.039 to 2.179), p = 0.059]." (PMID 27104116, 2016). "At univariate analysis, patients with septic shock were significantly older, a higher proportion had hypertension, lower platelet count and serum albumin level, higher CRP and PCT level, and higher positive blood culture rate." (PMID 27256181, 2016). "IL-6 stimulates the synthesis of C-reactive protein and also promotes VSMC proliferation, a hallmark of hypertension and atherosclerosis." (PMID 26989902, 2016). "OxLDL and oxLDL/HDL were strongly correlated with DBP, and CRP was weakly correlated with DBP, but HbA1c was the only biomarker associated with a self-report of high blood pressure." (PMID 26938991, 2016). "Our findings are consistent with the previous reports indicating that hypoadiponectinemia is a strong predictor of future hypertension, even after adjusting for the confounding systemic factors, such as mean blood pressure, C-reactive protein, BMI, and WC." (PMID 26146630, 2015). "Elevated levels of C-reactive protein (CRP), as a measurement of systemic inflammation, are associated with hypertension, type 2 diabetes (T2D), coronary artery disease (CAD), stroke, peripheral artery disease, and mortality." (PMID 25768928, 2015). "Frequency of hypertension, smoking, alcohol consumption was higher for patients than controls (P <0.05), and levels of TC, hs-CRP and GLU were higher (P <0.05)." (PMID 26334877, 2015). "Hypertension (P = 0.018) and hyperlipidemia (P = 0.025) were significantly more common in the top CRP tertile than in the bottom two tertiles." (PMID 26308525, 2015). "Remarkably, the levels of CRP in patients with any cardiovascular disease defined as hypertension, ischemic heart conditions, coronary heart disease or stroke were not substantially different from that in non-cardiovascular diseases." (PMID 25638154, 2015). "Despite positive mutual correlations, both CRP and oxLDL were strong multivariate predictors for incident hypertension in our group of lone AF patients." (PMID 26229238, 2015). "Severe SRBD was significantly associated with elevated levels of CRP (3.7 [1.8–7.0] mg/l, vs. moderate (p = 0.001), and mild SRBD (p<0.001), and higher prevalence of hypertension as compared to moderate and mild SRBD (p<0.001, respectively)." (PMID 26356577, 2015). "Classical CV risk factors (age, smoking, hypertension, lipid profile, BMI, FSS) and RA-related factors (disease duration, RF, ACPA, DAS28, ESR, CRP, bone erosions) were assessed and their associations with plaque presence and IMT were analyzed." (PMID 26648990, 2015). "In general, individuals who have high blood pressure, exercise less, are overweight, and smoke tend to have high levels of CRP." (PMID 26406989, 2015).
Hypertension (continued). "The naïve AUC was 0.728 (95% confidence interval [CI]: 0.705, 0.751) for the logistic model with the significant risk factors including sex, hypertension, BMI, FPG, HbA1c, and log-transformed CRP as predicting variables." (PMID 24819157, 2014). "When we evaluated the associations between the CRP-related SNPs with cardiovascular disease phenotypes, rs9375813 (ARG1) showed a marginal association with hypertension (P = 0.0440)." (PMID 24763700, 2014). "We conducted logistic regression analysis to evaluate the associations between CRP-related SNPs with disease phenotypes such as CHD (n = 65), myocardial infarction (MI; n = 55), and hypertension (n = 1,115)." (PMID 24763700, 2014). "Individuals with pre-hypertension or with shorter duration of hypertension (≤ 1 year, stage 0) had significantly a greater likelihood of hs-CRP elevation compared with chronic stage 1 or 2 hypertensive." (PMID 25237581, 2014). "In the present study, we aim assess mental well-being with presence of hypertension, hyperuricemia and hs-CRP." (PMID 25237581, 2014). "Prehypertensive patients generally have higher plasma CRP levels than normotensive patients, and higher baseline CRP levels are reportedly associated with a higher risk of developing overt hypertension, consistent with the concept that systemic low-grade inflammation may precede hypertension." (PMID 25136585, 2014). "High CRP levels are known to be associated with cardiovascular disease (CVD) risk factors, including hypertension, coronary heart disease (CHD), and stroke, in addition to traditional risk factors such as BMI, smoking, diabetes, and cholesterol levels." (PMID 24763700, 2014). "It has been demonstrated that monocyte count is a better independent risk factor of CVD than several conventional risk factors such as C-reactive protein (CRP), inflammatory cytokine interleukin-6 (IL-6), fibrinogen, hypertension, and cigarette smoking." (PMID 24398220, 2014). "Female gender, hypertension, BMI, FPG, HbA1c, and CRP were all significantly associated with incident T2DM during the 6-year follow-up period." (PMID 24819157, 2014). "Across Prx4 tertiles, individuals with higher Prx4 levels were older, more obese, less frequent alcohol drinkers and more likely to have hypertension and higher cholesterol, triglycerols, glucose, hs-CRP, procalcitonin and 24 h UAE." (PMID 24893865, 2014). "Association between aldosterone and inflammation has been reported in essential hypertensive patients, where high plasma aldosterone levels were correlated with high levels of circulating CRP and leukocytes." (PMID 25136585, 2014). "Substantial correlations between CD45−CD34+ and conventional cardiovascular risk factors (hs-CRP, T2DM, serum uric acid and hypertension) were found in the patient cohort." (PMID 26237060, 2013). "Multiple linear regression revealed that CRP was influenced by hypertension (P = 0.026) and cognitive impairment (P = 0.042)." (PMID 23978069, 2013). "Clinical parameters associated with the presence of subclinical carotid atherosclerosis were old age, previous history of hypertension, increased pulse pressure, and higher high-sensitivity C-reactive protein (hs-CRP) level." (PMID 24192205, 2013). "Only two CPGs (IND and JAP) recommended assessing C-reactive protein as part of the workup for patients with hypertension." (PMID 23349738, 2013). "A group of persons, which were surveyed, were predominantly males (58.7%) at the age of 58.34 ± 9.60 years, with mean HbA1c level equal to 6.8%, with hyperlipidemia, mild-to-moderate increase of hs-CRP, and history of hypertension." (PMID 23607043, 2013). "Regression analysis revealed that hypertension and cognitive impairment led to the elevation of CRP in serum." (PMID 23978069, 2013). "Patients with ACS were older with higher prevalence of hypertension, worse kidney function and higher hs-CRP than NS patients." (PMID 24028208, 2013).
Hypertension (continued). "Among men, CES-D scores correlated positively with high-sensitivity C-reactive protein (P < .05), and odds of hypertension increased by 21% with each 5-unit increase in CES-D scores." (PMID 24151548, 2013). "Data concerning glomerular filtration rate (GFR), number of vessels with stenosis, hypertension, lipid disorders, creatinine concentration, C-reactive protein, glucose and lipid profile were analyzed." (PMID 23483304, 2013). "A strong modulatory effect of DM2 on plasma fibrin clot phenotype has been observed in the presence of several factors leading also to the formation of more dense and less lysable clots such as smoking, hypertension and elevated CRP levels." (PMID 23086579, 2013). "Some years ago we demonstrated that ultrasensitive C reactive protein (uCRP), a marker of low grade inflammation, was increased in individuals with hypertension." (PMID 23573414, 2013). "Hypertension induced by IP infusion of LPS was accompanied by an increase in plasma levels of CRP, TNFα, and IL-1β, detected on day 7 or 14 after infusion of the endotoxin." (PMID 22958438, 2012). "The aim of this study was to investigate the contribution of CRP, cortisol and hypertension to the increased likelihood of cardiovascular disease in both African and Caucasian women from South Africa." (PMID 22447476, 2012). "In the multivariate logistic regression analysis, the risk factors for cardiovascular morbidity in this cohort included old age, smoking, hypertension, hypertriglyceridemia, low level of hemoglobin, and elevated levels of C-reactive protein." (PMID 22935444, 2012). "With a comparable increase in plasma CRP of 27±5% on IP infusion of LPS, our animal model should suitably predict augmented risks of the rats in developing hypertension." (PMID 22958438, 2012). "In an earlier clinical study, development of vascular diseases and hypertension is more prevalent in participants with an approximately 35% increase in plasma CRP." (PMID 22958438, 2012). "It is therefore imperative that the relationship between cortisol, CRP and vascular responses, and the prevalence of hypertension be explored further in the ethnic groups of South Africa in order to fully substantiate and assess possible risk for CVD." (PMID 22447476, 2012). "After additional adjustment for LDL cholesterol, hypertension, diabetes type 2, etiology (model 2), and CRP and Nt-proBNP (model 3), this relationship remained significant." (PMID 22427939, 2012). "Intraperitoneal infusion of LPS (1.2 mg/kg/day) for 14 days promoted sustained hypertension and induced a significant increase in plasma level of C-reactive protein, tumor necrosis factor-α (TNF-α), or interleukin-1β (IL-1β)." (PMID 22958438, 2012). "This relationship remained significant for CV death, but not for total mortality also after adjustment for age, creatinine levels, LDL cholesterol, hypertension, diabetes type 2, CRP and Nt-proBNP (model 2)." (PMID 22427939, 2012). "Further studies should be performed to assess more precisely the relationships between CRP and NO and their role in the regulation of membrane functions and circulatory mechanisms in hypertension." (PMID 22518282, 2012). "The present study was designed to evaluate the relationship between high-sensitivity C-reactive protein (hs-CRP) and arterial stiffness according to sex in patients with arterial hypertension." (PMID 22676422, 2012). "The children who were obese and unfit were significantly more likely to have high blood pressure, cholesterol, CRP and fasting insulin levels." (PMID 22693553, 2012). "A large-scale prospective, double-blind, placebo-controlled, multicenter study performed in patients with essential hypertension and microinflammation also showed that olmesartan therapy significantly reduced the serum level of CRP." (PMID 22583484, 2012).
Hypertension (continued). "Another study determined that CRP, an inflammatory marker, known to be elevated in metabolic syndrome, is a better predictor of oxidative stress in “essential” hypertension, than high blood pressure." (PMID 22829804, 2012). "The independent correlates of VEGF, accounting for 6 percent of its variance were CRP, hypertension, less than a high school education, current smoking and triglycerides." (PMID 21672190, 2011). "Hypertension develops through increased chemokine and cytokine expression, induction of the renin-angiotensin system and increased vascular C-reactive protein (CRP) expression." (PMID 20222993, 2010). "Apart from the dominant effect of aging, they include smoking, visceral obesity, triglyceride, CRP, hypertension, and hyperglycemia." (PMID 21187863, 2010). "Participants with abnormal circadian BP variability disorders: M-Hypotension (n = 5) had hs-CRP concentration of 19.2 ± 3.1 mg/L (p < 0.05), with M-Hypertension (n = 2) 3.1 ± 0.1 mg/L (p < 0.05), with CHAT (n = 1) 20.2 mg/L and with EPP (n = 4) 10.9 ± 6 mg/L." (PMID 20868493, 2010). "Conventional risk factors were more frequent among patients with IL-10 concentrations above median, including elevation of CRP and IL-6 but excluding previous MI and hypertension." (PMID 17690160, 2008). "There was nosignificant correlation between average diameter of CAE and hs-CRP(r = 0.244, P = .129), and a weak correlation wasobserved between average ectasia diameter and hypertension (HT)(r = 0.300, P = .06)." (PMID 17497040, 2007). "Subjects with AF had a higher prevalence of electrocardiographic LVH, ischemic heart disease, hypertension, renal dysfunction, and higher levels of CRP and urinary albumin excretion as compared to age and gender matched controls." (PMID 16623947, 2006). "Subjects with AF had a higher prevalence of electrocardiographic left ventricular hypertrophy, ischemic heart disease, hypertension, renal dysfunction, elevated levels of C-reactive protein (CRP) and increased urinary albumin excretion as compared to controls." (PMID 16623947, 2006). "Hypertension promotes vascular injury and endothelial dysfunction, which stimulate cytokine release and hepatic CRP synthesis, and CRP itself aggravates hypertension by reducing nitric oxide, enhancing oxidative stress, and creating a general inflammatory state in the body." (PMID 41515269, 2026). "Five predictors were retained by LASSO-prognostic nutritional index (PNI), erythrocyte sedimentation rate (ESR), C-reactive protein (CRP), chronic disease stage, and hypertension-and combined with age and sex (retained a priori) into a seven-predictor nomogram." (PMID 41899105, 2026). "Furthermore, fibrinogen levels were positively correlated with CRP (r = 0.50) and with comorbidities such as hypertension in 66 (70.97%) patients and chronic kidney disease in 20 (21.51%) patients." (PMID 40151482, 2025). "Moreover, FBG, hs‐CRP, BMI, WC, hypertension, physical activity, smoking status, drinking status, family cancer history, and lipid‐lowering therapy differed significantly among different cancer groups." (PMID 39912426, 2025). "Additionally, significant differences were observed among participants across various baseline characteristics, including age, gender, marital status, residence location, hypertension status, smoking, TG, CRP, HbA1c, BMI, and WC (all P < 0.05)." (PMID 41171818, 2025). "Univariate analysis showed that APACHE II score, hypertension, leukocytes, total bilirubin, C-reactive protein, hypersensitive troponin I, P/F ratio, lactic acid, SOFA score, tidal volume, respiratory rate, vasoactive drugs, and fluid balance at 24 h were statistically significant (p < 0.1)." (PMID 40225039, 2025). "Systemic inflammation is closely associated with vascular alterations, including endothelial dysfunction and increased arterial stiffness and traditional markers of inflammation, such as C-reactive protein (CRP), have been associated with hypertension in large-scale studies." (PMID 41377914, 2025).